IL4 (interleukin 4)
Diseases named in the same sentence as IL4 in open-access papers (continued):
Sharing a sentence is not in itself a finding about the gene and the disease.
infection (continued). "Similarly, MLN cells from infected Se-adequate mice expressed higher secretion of IL-4 during the early period of infection (day 7 of infection) following 24–48 h of re-stimulation (P<0.01) than those isolated at days 14 or 21 of infection." (PMID 19247447, 2009). "IL-4 may therefore provide a regulatory mechanism to antagonise necrosis-inducing factors but in doing so may also shift infection from latency to disease." (PMID 19156215, 2009). "Mice genetically deficient in IL-4, IL-13, or IFN-γ alone or in combination were infected with S. mansoni cercariae and expression of Retnla was measured in the liver by quantitative RT-PCR 9 wk post-infection." (PMID 19381262, 2009). "Thus, local and systemic levels of IL-6, IL1β, TNF-α, MIP-1α, and MIP-2 were compared between IL-4−/− and control mice at 2, 5, and 10 days after infection." (PMID 19606256, 2009). "To determine whether there was selective depletion of Th17 cells over other Th populations (e.g., those producing IFNγ, IL-4, or MIP1β) we measured the ratio between Th17 cells and these other populations as a function of time post-infection." (PMID 19214220, 2009). "In this paradigm, control of infection and healing have been associated with a polarized Th1 response whereas non-healing has been ascribed to an interleukin (IL)-4-dominated polarized Th2 response." (PMID 19597544, 2009). "We were unable to detect the secretion of IL-4 or IL-5 during any stage of the infection." (PMID 18544042, 2008). "Pro-inflammatory cytokines such as IL-1β, IL-4, IL-6 and IL-7 participate in this infection." (PMID 17935610, 2007). "This may be a direct effect of infection, as Helicobacter activates NF-κB via chronic inflammation and the activation of interleukins, such as IL-4, or in response to lipopolysaccharides and NF-κB in turn is able to activate Shh." (PMID 17505514, 2007). "In peritoneal cells from mice infected i.p. production of IL-4 could be detected at day 5 of infection." (PMID 16076403, 2005). "Also, its lower IL-4 competence compared to the other LNs during infection could foster its GC-forming ability." (PMID 40092986, 2025). "Moreover, IL4 contributes to increased antibody responses during infection." (PMID 40667878, 2025). "Moreover, when co-inoculation of anti-Acr IgA TBA61 mAb and mouse IFNγ via i.n. route in Balb/c mice with IL-4 depletion by a neutralizing anti-IL4 mAb, a significant reduction of bacterial burdens can be observed compared with IgA and IFNγ treatment in wild-type mice after H37Rv infection." (PMID 41200176, 2025). "Comparative acute-phase profiling of acute CHIKV and DENV infection also found IL-8 (and IL-4) upregulation in both infections, with CHIKV-specific downregulation of IL-13 and MCP-3 and age-associated differences; ex vivo PBMC infection recapitulated the IL-8/IL-13/MCP-3 pattern (but not IL-4)." (PMID 41346606, 2025). "The significance of ILC2s activation during CR infection could lie in production of IL-4 and IL-13 to drive mucus production, in addition to IL-5 which can act synergistically with IL-4 to influence or enhance an antibody response, promoting bacterial clearance." (PMID 40591723, 2025). "In addition to the increased participation of CD8+ T cells in the production of IFN-γ, these cells also produced other cytokines, such as IL-10 and IL-4 denoting a mixed response of the inflammatory profile after infection, predominantly directed by CD8+ T cells." (PMID 40006676, 2025). "This fact shows that the infection may be modulating the production of IL-4 by these cells." (PMID 40006676, 2025). "The study of Wang, Liang53, Li, Wang54, and Hu, Ye55 have suggested that MP infection can suppress the cellular immunity, while the humoral immunity is in an overactivated state, which denotes that the increase in IL-4 may be more significant compared to the increase in IFN-γ." (PMID 39572779, 2024).
infection (continued). "IL-5, IL-4, and IL-3 could attenuate the anti-Candida response in the WT-infected group, and a combination of both allows the fungal cells to thrive and induce tissue damage and death within 8 days of WT infection." (PMID 38783167, 2024). "Therefore, we demonstrate that IL-4 derived from eosinophils during early stage of infection could consequently promote generation and function of memory CD8+ T cell." (PMID 38413575, 2024). "However, the polarized type 2 response (IL-4, IL-5, IL-9, and IL-13) might reduce the severity of infection and contribute to the nematode parasite's eradication." (PMID 39103392, 2024). "In addition, IL-4 downregulated the expression of cleaved caspase-3 in CD8+ T cells upon infection." (PMID 38413575, 2024). "Therefore, we can speculate that a lower production of IL-4, a Th2 anti-inflammatory cytokine, is normal initially, as the infection is being countered with the production of mainly pro-inflammatory cytokines." (PMID 38543749, 2024). "Therefore, further research is warranted to explore the source of IL-4 after infection." (PMID 39287443, 2024). "IL-4 also promotes B cell class switching to produce IgE antibodies, which not only have a role in allergic reactions but contribute to host defense against parasites and certain infections, facilitating pathogen neutralization and modulation of immune responses." (PMID 38251210, 2024). "LAG3 deficiency increased IFN-γ and decreased IL-4 secretion by T cells, but we did not observe significant alterations in Foxp3+ Treg differentiation and function, which led to failure to inhibit the growth of metacestodes in the middle stage of infection." (PMID 37172058, 2023). "The TT polymorphic genotype for IL4 -560C/T was associated with a greater chance (almost three times) of the individual developing TB among those infected by Mtb (TB vs. LTBI) and of having the infection and developing disease (comparison between the TB and control groups)." (PMID 37892223, 2023). "Therefore, the comparison between mice strains shows that BALB/c mice have higher values of the proinflammatory cytokines (IFN-γ and IL-6) and the anti-inflammatory cytokines (IL-10 and IL-4) in response to infection than C57BL/6 mice (Welch two-sample t test, P < 0.05)." (PMID 37140369, 2023). "Interestingly, application of schistosome eggs, a strong inducer of IL-4 and IL-13 production in vivo, prior to infection of mice with Salmonella typhimurium downregulated the Th17 response in the gut mucosa and impaired the clearance of the bacteria from the gut." (PMID 36753434, 2023). "In line with the modest contribution of Th2/1 cells to IL-4 and IL-13 production and their identification as the main source of parasite-specific IFN-γ production, expanded Th2/1 hybrid cells lead to a further delay in the control of infection in highly susceptible C57BL/6 mice." (PMID 35690651, 2022). "Our data revealed the induction of a heterogenous iNKT cell response during infection which, surprisingly was dominated by the activation of iNKT cells with a mixed type 1/type 2 immune signature and pronounced production of type 2 cytokines, such as IL-13 and IL-4." (PMID 36159876, 2022). "Additionally, positive TNF-α+, IFN-γ+, and IL-4+ mCD4+ T cells could still be detected in the infection-only group." (PMID 36494338, 2022). "Thus, we believe that in the initial phase of infection by T. canis, the cytokines IL-17A and IL-4 are the main active components, however, a synergistic action with other components of the immune system is necessary for a more effective and controlled response." (PMID 35844540, 2022). "However, in KO rats following infection with S. japonicum, the significant increase of IL-4-producing CD4+ T cells frequency was only found in the blood but not in the LN and spleens, in which the magnitude of increase between naïve and infected groups was lower than those found in the WT rats." (PMID 35584107, 2022).
infection (continued). "Apart from B cells, in patients with active pulmonary tuberculosis, IL-4 secretion from BAL cells revealed a strong association with acid-fast Mycobacterium tuberculosis bacilli staining in sputum smear, suggesting a permissive Th2 environment at the site of infection." (PMID 34220793, 2021). "Thus, it is revealed that IL-4 promotes the expression of AAM gene in the early-life infection." (PMID 34226412, 2021). "Compelling evidence has revealed the augmented IL-4 gene expression in abomasal tissue early after H. contortus infection, while the observation of elevated serum IL-4 production may vary among early, mid and late infection partly dependent on inoculation dose and animal breeds." (PMID 33407892, 2021). "Similarly, the MFI of Ym1 on CD11c+CD11b+ cells was significantly decreased as was the number of CD11c+CD11b+ cells expressing Ym1 at 30 days post-infection in P. murina infected IL-4−/− neonates, consistent with Ym1 expression being partially driven by IL-4 in response to P. murina." (PMID 34682248, 2021). "Overall, our results concur with a broader Th profile in CD8+T cells induced by the nonspike viral proteins and associated with a less severe infection, while spike responses dominated by IL-4+ CD8+T cells represented a hallmark of disease severity, being the sole response in the fatal case." (PMID 34021148, 2021). "Similarly, only T. muris-infected C57BL/6 but not BALB/c mice are susceptible to the infection in the absence of IL-4." (PMID 33983946, 2021). "IL-4-treated macrophages could assume a wound-healing phenotype, which facilitate matrix reorganization and tissue repair, whereas, possess poorer pro-inflammation and anti-infection abilities than M1 macrophages." (PMID 35059401, 2021). "Thus, in our model, we accessed the bronchoalveolar lavage levels of cytokines associated with different cellular profiles, IL-4 and IL-13 (Th2), INF-γ (Th1) and IL-17 (Th17) of XID and BALB/c mice before infection (day 0) and 7 and 9 days after infected with C. gattii." (PMID 34526536, 2021). "Having demonstrated the anti-colitic effect of M(IL4)s and the preservation of gut barrier function, the current study yielded no data to suggest that M(IL4) therapy would exaggerate or leave an individual more vulnerable to concomitant infection, CRC or airways inflammation." (PMID 34691050, 2021). "At the same time, downregulation of Th2 cytokines, such as IL4/IL13, as well as IL10 and TGFβ, which are primarily associated with tissue repair and extracellular matrix composition, was observed during the late stage of infection, especially in infected fish at 11°C." (PMID 32695119, 2020). "Likewise, Th2-type cytokines, e.g., IL-4 and IL-10, were assessed for their functional effects in periapical bone destruction in a genetic study, which revealed the suppressive role of IL-10, but not IL-4, on infection-induced periapical bone loss." (PMID 32116745, 2020). "In addition to altering the neurological behavior, IL-4 can also enhance immunity against A. cantonensis infection by activating B cells and inducing a class switch of IgE, which helps in defending parasite infection." (PMID 32635653, 2020). "This factor's crucial role is neatly illustrated in Hymenolepis diminuta infection; STAT-6 knockout mice infected with this tapeworm were unable to clear this infection due, in part, to diminished goblet cell response, unlike their IL-13 and IL-4 deficient counterparts at 12 days post-infection." (PMID 33013869, 2020). "Moreover, in Brazilian patients with PCM, reports of polymorphisms on IL-4 and IL-12Rβ1 genes have shown the relevance of IL4-590 C/T and IL12RB1 641 A/G SNPs in association with infection or clinical forms, contributing to a better understanding of the immunopathogenesis of this disease." (PMID 33117339, 2020).
infection (continued). "However, IL-4 production by eosinophils and antigen-specific Th2 cells occurred rather late during infection, suggesting that other IL-4 sources may contribute to Th2 polarization at early time points of the infection process." (PMID 32117319, 2020). "The animals that received carrageenan injection treated with MFS showed higher levels of IL-4, which inhibits chemotaxis and migration of neutrophils to the point that systemic inhibition of IL-4 increases the influx of CD11b+Ly6G+ cells (neutrophils) during infection." (PMID 33424619, 2020). "However, IL-4 produced by CD4+ T helper type 2 cells (Th2 cells) in Th2 responses inhibits Th1 responses and macrophage activation, which helps parasites survive and results in susceptibility of the host to severe infection." (PMID 32176727, 2020). "Moreover, the ΔADSL mutant also generated high levels of Th1 (IFN-γ and IL-12) immunity and elevated Th2 (IL-4) protective immunity, as indicated at 30 and 70 days post-immunization, and protected animals from further infections with various T. gondii wild-type strains." (PMID 31935935, 2020). "Finally, we compare the simulated dynamics between single- and dual-infected rabbits and, although we cannot draw direct analogies for specifc IgA responses, because of the different antigens used, we can highlight some general trends and also examine the intensity of infection and IL4." (PMID 33226981, 2020). "After a 2 h infection period, residual extracellular Cn were removed by washing and the cells were cultured for a further 24 h in growth medium containing either IFNγ to maintain the M1 polarization state or IL-4 to repolarize to M2, with the growth medium and cytokines replaced at 6 h intervals." (PMID 32857777, 2020). "However, the IL-4 level was drastically higher in the WT-infected mice at every stage of infection." (PMID 33224112, 2020). "Interestingly, LmJ3OE infections displayed a significantly lower expression of IL-4 and IL-10." (PMID 33114674, 2020). "While it is known that parasites migrate from the site of infection to the lesion-draining lymph nodes, we were interested to determine if L. major parasites were using CD11b+ Mo-DCs or CD11b+ cDCs to disseminate to peripheral organs, and if IL-4/IL-13 signaling influenced this process." (PMID 32039054, 2019). "However, the presence of macrophage inhibitory cytokines such as IL-4 present in the site of infection can cause non-healing chronic lesions." (PMID 30642262, 2019). "In addition, the response in the spleen, which did not harbor any infection at all, was primarily concentrated about genes encoding immunoglobulins (IgM and IgT) and cytokines associated with humoral immunity (IL-4/13)." (PMID 31220151, 2019). "However, the single infections did induce IL-4, similarly to that described for IFNγ (p < 0.05)." (PMID 29942312, 2018). "Moreover, significant elevations in the levels of plasma Th2 cytokines (IL-4, IL-13, and IL-10) and serum enzymes (alanine aminotransferase and aspartate aminotransferase) reflecting altered liver function were detected in response to the infection." (PMID 30619361, 2018). "Furthermore, we also observed TVM expansion during other helminth-driven IL-4 dominated responses such as natural infection with N. brasiliensis at day 10 pi, and a significant TVM expansion and Eomes upregulation could also be observed by day 35 pi." (PMID 30375396, 2018). "Therefore, we wondered whether CXCR3− and CXCR3+ NKT cells would have a differential ability to produce IL-4 after infection." (PMID 29249358, 2018). "Interestingly, since it has been shown that IL-4 can potentiate infectivity, it is possible that the mosquito bite could be enhancing for infection through its induction of IL-4." (PMID 30135238, 2018). "However, the levels of IFNγ, IL-4 and IL-5 were elevated in Stat2−/− mice during super-infection." (PMID 30337919, 2018).
infection (continued). "Moreover, infected pigs show an important decrease in CD8+ T-cells and IFN-γ production and a reduction of 50 to 80% of NK cell cytotoxicity from day 7 to 24 post infection maybe due to increased IL-4 levels." (PMID 30504834, 2018). "Since HTLV-1 entry pathways, and intracellular localization are similar in immature IL-4 DCs that are susceptible to infection and in IFN-α DCs that are resistant to infection, we next wondered whether intravesicular pH could modify the ability of the virus to establish a productive infection." (PMID 28426803, 2017). "Conversely, susceptibility to infection and disease progression in CL is driven predominantly by the induction of a non-protective IL-4 Th-2-type response and the production of Th-2 associated cytokines such as IL-4, IL-10, IL-13 and transforming growth factor (TGF)-β." (PMID 27094260, 2017). "It promotes IFN-γ and IL-4 secretion and stimulates the Th1 response at the early phase of disease development by enhancing the phagocytosis of pathogens, thus preventing further harm from infection, which is synergistically supported by the upregulation of sIgA." (PMID 28577529, 2017). "B-cell-deficient μMT mice, nude mice, IFN-γ−/−, and IL-4−/− mice immunized with DnaJ-ΔA146Ply could not resist infection with pneumococci." (PMID 28659923, 2017). "Interestingly, IL-4 enhanced infection was reduced in D3-MDM by restriction of MR expression." (PMID 29020083, 2017). "Targeting IL-4 at the infection site could be of potential interest in the design of vaccines." (PMID 29067025, 2017). "However, high FEC with elevation in serum antibodies and IL-4 might confirm the incidence and progression of infection." (PMID 28717322, 2017). "Moreover, IL-4 and IL-13, key cytokines associated with M2 macrophages, were not modulated by the infection or the absence of Ebi3 in the hearts of animals." (PMID 29033934, 2017). "Collectively, these and our data suggest that the early presence of IL-4 may have a different impact on the development of Th1 response depending on the dose of parasite inoculated, the genetic background of the mice, and the local amount of IL-4 protein present at the site of infection." (PMID 29067025, 2017). "Unlike what was observed following L. major infection, IL-4-deficient mice failed to develop Th1 cells in response to infection with Candida albicans suggesting a potential role for endogenous IL-4 in Th1 cell differentiation and protective antifungal response." (PMID 29067025, 2017). "However, in a more permissive host, yellow cattle, IL4 shows an increase after infection." (PMID 29253882, 2017). "Thus, it is plausible that M(IL-4) cells possess novel undefined characteristics that need to be uncovered regarding how they may regulate immunity during infections." (PMID 29250063, 2017). "After secondary infection of Il4rafl/fl mice, the proportion and absolute number of ex-Foxp3 Th2 cells were significantly reduced compared with Hp 2° Il4rawt/wt mice, demonstrating a fundamental requirement for IL-4 signaling in Foxp3-expressing cells for the development of ex-Foxp3 Th2 cells." (PMID 28507062, 2017). "Interestingly, IL-4 was dispensable in this infection model." (PMID 27895717, 2016). "However, in the Ft infection model we observed no decrease in Th2 cytokines such as IL-4 or IL-10 in Nlrp3-deficient mice at any time following infection, but IFNγ production was slightly elevated at 6 days post-infection." (PMID 27926940, 2016). "To investigate how IL-33 might interfer with the host immune response, we measured the levels of the key Th1 cytokines (IFN-γ, IL-12 and TNF-α), key Th2 cytokines (IL-4, IL-5 and IL-13), and the regulatory cytokine IL-10 in the serum at various time-points after infection with PbA." (PMID 25659095, 2015). "Thus, simultaneous production of high IL-4 and IL-10 may be the mechanistic determinant of the exacerbated infection observed in the spleen of saponin + LAg immunized mice." (PMID 24428931, 2014).